ACVR2B (activin A receptor type 2B)
Diseases named in the same sentence as ACVR2B in open-access papers (continued):
Sharing a sentence is not in itself a finding about the gene and the disease.
Telangiectasia (2 papers, 2019 to 2022). Telangiectasias refer to small dilated blood vessels located near the surface of the skin or mucous membranes, measuring between 0.5 and 1 millimeter in diameter. "Indeed, the broad ligand specificity of ACVR2B-Fc increases the risk of toxicity to non-skeletal muscle tissues and cell types, ranging from epistaxis to telangiectasias." (PMID 36314781, 2022).
allergic asthma (1 paper, 2022). A asthma with a basis in a pathological type I hypersensitivity reaction. "ACVR2B belongs to the type II activin receptor class and activin-A has been implicated in several aspects of immunity with fundamental roles in allergic responses and tissue remodeling in human allergic diseases, including allergic asthma and AD54." (PMID 36482174, 2022).
anal prolapse (1 paper, 2017). "Due to the development of an anal prolapse, two ACVR2B/Fc treated R6/2 mice were culled (on days 106 and 122) and these were not included in the final analysis." (PMID 29079832, 2017).
Arthritis (1 paper, 2023). Inflammation of a joint. "From our collective findings, we conclude that the pathogenic ACVR2B assembly could affect various types of arthritis pathogenesis." (PMID 36950748, 2023).
asplenia (1 paper, 2018). "The spleen is reduced in mice lacking the NODAL receptor Acvr2b, although asplenia seems to be observed only in Cfc1 (Cryptic) mutants." (PMID 29992973, 2018).
bladder cancers (1 paper, 2025). "Of particular interest, expression of INHBA and ACVR2B were increased in bladder cancer in both males and females, as compared to adjacent normal bladder tissue." (PMID 40144023, 2025). "It is noteworthy that ACVR2B expression increased significantly in human bladder cancers of both males and females, whereas ACVR2A expression was unchanged." (PMID 40144023, 2025). "In addition to INHBA, reported as the most upregulated gene in human bladder cancer, we also observed upregulation of ACVR2B in bladder cancer." (PMID 40144023, 2025).
brain injury (1 paper, 2018). Acute and chronic (see also brain INJURIES, CHRONIC) injuries to the brain, including the cerebral hemispheres, CEREBELLUM, and brain STEM. "Consistent with this postulate, increased levels of Acvr2b mRNA in umbilical cord blood at birth is associated with more severe clinical outcome in infants following hypoxic-ischemic perinatal brain injury." (PMID 29397421, 2018).
encephalitis (1 paper, 2026). An acute inflammatory process affecting the brain parenchyma. "Across multiple feature selection algorithms, ACVR2B and MX1 were reproducibly prioritized as immune-associated candidate genes and were consistently downregulated in anti-NMDAR encephalitis samples, showing negative correlations with neutrophil infiltration." (PMID 41596688, 2026).
Facioscapulohumeral dystrophy (1 paper, 2008). Facioscapulohumeral muscular dystrophy (FSHD) is characterized by progressive muscle weakness with focal involvement of the facial, shoulder and limb muscles. "In an independent microarray study of 10 men and 9 women with facioscapulohumeral dystrophy, women had higher expression of GRB10 (2.7-fold, P<0.001) and ACVR2B (1.7-fold, P<0.03)." (PMID 18167544, 2008).
heart failure (1 paper, 2020). Inability of the heart to pump blood at an adequate rate to meet tissue metabolic requirements. "Because CRC induces cardiovascular complications including heart failure, we documented the effects of CRC LM on cardiac function using echocardiography and determined if ACVR2B signalling blockade counteracted tumour‐associated cardiac dysfunction." (PMID 33200567, 2020).
hypertrophy (1 paper, 2019). Hypertrophy is the increase in the volume of an organ or tissue due to the enlargement of its component cells. "ACVR2B-Fc modified cardiac metabolism, LV mitochondrial respiration, as well as cardiac phenotype toward physiological hypertrophy." (PMID 30765322, 2019).
metabolic myopathy (1 paper, 2017). A group of rare inherited disorders characterized by a deficiency of enzymes that are involved in metabolic pathways that affect muscles. "Recently, it has been found that blockage of ACVR2B induces hypertrophy, but is accompanied by increased muscle metabolic myopathy." (PMID 27733450, 2017).
multiple sclerosis (1 paper, 2018). A progressive autoimmune disorder affecting the central nervous system resulting in demyelination. "Indeed, regions that were actively myelinating (in perinatal tissue) or remyelinating (in multiple sclerosis lesions) demonstrated relatively higher densities of oligodendroglial lineage cells expressing Acvr2a compared to those expressing Acvr2b." (PMID 29397421, 2018). "In actively myelinating or remyelinating areas of human perinatal brain injury and multiple sclerosis tissue, respectively, oligodendrocyte lineage cells expressing Acvr2a outnumbered those expressing Acvr2b, whereas in non-repairing lesions Acvr2b+ cells were increased." (PMID 29397421, 2018).
myeloma (1 paper, 2015). "In myeloma cells, BMP-6- and BMP-9-induced activation of SMAD1/5/8 through ACVR2A/ACVR2B/ALK2 was inhibited by activin A treatment." (PMID 26047946, 2015). "Thus, ALK2, ACVR2A and ACVR2B are candidate mediators of the antagonizing effects of activin A on BMP-6 and BMP-9 signaling in myeloma cells." (PMID 26047946, 2015). "Moreover, ACVR2A, ACVR2B and ALK2 are ubiquitously expressed and knowledge about regulation of signaling through these receptors might have general implications, for instance in bone homeostasis in myeloma patients." (PMID 26047946, 2015). "Using myeloma cell lines as a model system, we show that activin A antagonizes BMP-6 or BMP-9-signaling through ACVR2A/ACVR2B/ALK2, but not BMP-2 or BMP-4-signaling through BMPR2/ALK3 or BMPR2/ALK6." (PMID 26047946, 2015).
myocardial ischemia (1 paper, 2019). A disorder of cardiac function caused by insufficient blood flow to the muscle tissue of the heart. "report that systemic blockade of activin receptor type 2 (ACVR2B) ligands protects from cardiac ischemia-reperfusion injury reducing infarct size, apoptosis, and autophagy." (PMID 30765322, 2019). "Mice were treated with soluble ACVR2B decoy receptor (ACVR2B-Fc) and subjected to myocardial ischemia followed by reperfusion for 6 or 24 h." (PMID 30765322, 2019).
neuroblastoma (1 paper, 2017). Neuroblastoma (NB) is the most common solid, extracranial childhood tumor. "Specifically, we found that, for MYCN amplified neuroblastoma, pairwise expression of ACVR2B or anaplastic lymphoma kinase (ALK) with GFRA3, GFRA2, Cadherin 24, or with one another provided the strongest hits." (PMID 28871274, 2017).
osteoarthritis (1 paper, 2023). A noninflammatory degenerative joint disease occurring chiefly in older persons, characterized by degeneration of the articular cartilage, hypertrophy of bone at the margins and changes in the synovial membrane. "Although activin receptor IIB (ACVR2B) is emerging as a novel pathogenic receptor, its ligand and assembled components (or assembly) are totally unknown in the context of osteoarthritis (OA) pathogenesis." (PMID 36950748, 2023).
perinatal asphyxia (1 paper, 2019). A disorder caused by a lack of blood flow or gas exchange to or from the fetus in the period immediately before, during, or after the birth process. "Despite the lack of confirmation of a significant increase in activin-A levels, as previously demonstrated in biological fluids following perinatal asphyxia and HIE, significantly increased levels of ACVR2B were detected in infants with severe HIE." (PMID 30984006, 2019).
prediabetes (1 paper, 2025). "miR-192 was up-regulated in obese prediabetes and targeted PIK3R4, ACVR2B, and inflammatory mediators such as TNFα and IL-1β." (PMID 41400625, 2025).
sarcoma (1 paper, 2023). A usually aggressive malignant neoplasm of the soft tissue or bone. "High expression levels of both ACVR2B and NFYA were in positive correlation with higher risk scores, suggesting that these two genes may act as risk factors for sarcoma development and clinical deterioration." (PMID 36769292, 2023). "Therefore, the association between overexpressed ACVR2B and poor prognosis of patients with sarcoma suggests a possibility of utilizing ACVR2B antagonists in reliving the cachemic effect of sarcoma and the therapy-induced loss of muscle mass, which has not yet been investigated." (PMID 36769292, 2023).
situs inversus (1 paper, 2022). A congenital condition in which there is complete right-to-left reversal of the position of the major thoracic and abdominal organs (that is, they are arranged in a mirror image of the normal positioning). "Furthermore, we detected candidate variants in GJA1 and ACVR2B possibly associated with situs inversus." (PMID 35547246, 2022).
Stroke (1 paper, 2023). Sudden impairment of blood flow to a part of the brain due to occlusion or rupture of an artery to the brain. "Moreover, Acvr2B expressions were inhibited in PE-treated stroke rats after injection with anti-activin-A antibody." (PMID 36829205, 2023).
uterine tumors (1 paper, 2023). "We profiled the data from uterine tumors deposited to the cBioPortal of Cancer Genomics for mutations of the TGFβ signaling pathway and identified several mutations in TGFβ-related receptors (TGFBR1, TGFBR2, ACVR1B, ACVR1C, ACVR2A, ACVR2B) and transcription factors (SMAD2, SMAD3, SMAD4)." (PMID 36906706, 2023).
cancer (40 papers, 2011 to 2026). A tumor composed of atypical neoplastic, often pleomorphic cells that invade other tissues. "Upregulation of the ACVR2B pathway is involved in numerous types of cancer and is associated with cancer cachexia." (PMID 35326491, 2022). "Here, we demonstrate that the improved muscle mass and strength upon administration of ACVR2B/Fc was also associated with improvement in Stat3 phosphorylation, further highlighting Stat3 as a pivotal prognosticator of cancer‐induced muscle wasting." (PMID 33200567, 2020). "Investigations have been performed on the clinical potentials of the ACVR2B-signaling inhibitors in relieving multi-organ co-morbidities and cachexia-accompanying cancers, side effects of chemotherapy, and muscle damage caused by other diseases, such as ischemic heart failure." (PMID 36769292, 2023). "Another interesting gene that we have found upregulated is FST, an intrinsic inhibitor of activin; its encoded protein, together with ACVR2B (known as ActRIIB), may inhibit cancer cell growth via antagonizing activin signaling in our cell model." (PMID 31665064, 2019). "Hence, we investigated the muscle-protective properties of ACVR2B/Fc in the male mice only, due to their apparently enhanced susceptibility to the effects of anti-cancer agents." (PMID 29089584, 2017). "In contrast, activin A (Inhba), one of the main ligands bound by both FST and FSTL3 was primarily secreted by cancer cells, while its type II receptors (Acvr2a, Acvr2b) were highly expressed in both cancer cells and fibroblasts (Log2 FC > 0.5)." (PMID 41029436, 2025). "The strength of these findings corroborates the ACVR2B pathway’s emergence as a therapeutic target in cancer cachexia." (PMID 35326491, 2022). "A small number of genes specific for cancer at baseline were downregulated in APG-treated cancer patients after 3h and 24h (ACVR2B, CACNA1F, DONSON, PIH1D3, PRDM6)." (PMID 35600369, 2022). "Activin receptor type 2B (ACVR2B) signalling is known to cause SKM wasting, and its inhibition restores SKM mass and prolongs survival in cancer." (PMID 33200567, 2020). "Recently myostatin was identified in the secretome of C26 colon cancer cells and experimentally confirmed as novel tumoral factor that induces cancer cachexia via binding to ACVR2B." (PMID 27330885, 2016). "Altogether, our observations implicate ACVR2B signalling in the development of multi‐organ perturbations in metastatic CRC and further dictate that ACVR2B represents a promising therapeutic target to preserve body composition and functionality in cancer cachexia." (PMID 33200567, 2020). "Moreover, targeting ACVR2B signalling has shown to preserve fat and bone mass and mildly preserve cardiac size in experimental models of cancer‐induced and chemotherapy‐induced muscle wasting." (PMID 33200567, 2020). "Further examination of the critical insulin and glucose signaling pathways is warranted to better understand how ACVR2B/Fc treatment may mitigate some of the glucose derangements that occur with cancer-induced and chemotherapy-induced cachexia." (PMID 31438622, 2019). "In an attempt to isolate novel compounds endowed with muscle- and bone-protective properties, inhibition of the activin receptor 2B (ACVR2B) signaling was shown to enhance muscle mass, increase overall survival in experimental cancer cachexia, and to ameliorate the dystrophic phenotype in mdx mice." (PMID 29089584, 2017). "In addition, the current results suggest that blocking ACVR2B signalling may be a promising strategy to counteract chemotherapy-induced muscle and bone loss without further damage to skeletal muscle oxidative capacity or mitochondria or the actual treatment of malignancies." (PMID 27666826, 2016).
cancer (continued). "The pharmacological blockade of myostatin/activin pathway via the administration of an anti-myostatin monoclonal antibody that inhibit the binding of myostatin to its receptor ActRIIB/ACVR2B was found to be the most effective treatment for muscle wasting in cancer cachetic patients." (PMID 27330885, 2016). "Furthermore, acute inhibition of myostatin/ACVR2B signaling with the antagonist ACVR2B-Fc preserves skeletal muscle in mouse models of cancer cachexia." (PMID 21486491, 2011). "In this regard, targeting ACVR2B in combination with chemotherapy may prove to be a viable approach in minimizing tumour progression and the multi‐organ perturbations that occur with the progression of cancer cachexia." (PMID 33200567, 2020). "The mechanism responsible for the downregulation of BMPR2 in EBNA1-expressing and EBV-infected carcinoma cells in vitro is unclear, but the fact that these cells showed robust Smad1/5/8 phosphorylation suggests that ACVR2A or ACVR2B can substitute for BMPR2." (PMID 32708289, 2020). "Indeed, administration of ACVR2B/Fc, a synthetic decoy peptide and inhibitor of the signaling downstream of the binding of TGFβ family ligands to the activin receptor type 2B was able to potently preserve muscle mass and prolong survival in a model of cancer cachexia." (PMID 31447786, 2019). "Among the myriad factors known to contribute to skeletal muscle wasting resulting from cancer progression, members of the transforming growth factor (TGF)‐β superfamily, signalling via their binding to the activin receptor type 2B (ACVR2B), have received much attention." (PMID 33200567, 2020). "ACVR2B is a high affinity activin type 2 receptor that mediates the intracellular signaling induced by myostatin, activin and GDF11 in skeletal tissue, whose inhibition attenuate cancer cachexia." (PMID 27330885, 2016). "However, in pathological conditions such as tissue injury or cancer, this FST and myofibroblast barrier might be disrupted, allowing activin A to cross the FST barrier and activate the ACVR2B/ACVR1B receptor complex in urothelial cells as a paracrine signal." (PMID 40144023, 2025).
tumor (27 papers, 2012 to 2026). "Abundant staining of pSMAD3 and ACVR2B in tumor‐associated ADM extended our question to the role of activin A in tumor‐associated ADM." (PMID 37083240, 2023). "Additionally, we observed high expression of pSMAD3 and ACVR2B in tumor‐associated ADM regions, suggesting a potential role of activin A in tumor‐mediated ADM." (PMID 37083240, 2023). "In the tumor-to-tumor signaling direction, activin receptor type-2B (ACVR2B) was implicated in three of the fifteen top-scoring interactions with corresponding ligands of bone morphogenetic protein 5 (BMP5), growth differentiation factor 11 (GDF11), and inhibin beta C chain (INHBC)." (PMID 36676129, 2023). "It is also important to note that systemic myostatin administration has previously shown to induce fat wasting; hence, it is possible that ACVR2B/Fc administration prevents myostatin from acting directly on adipose tissue in the tumour‐bearing mice." (PMID 33200567, 2020). "Sham and tumour‐bearing mice received weekly injections of ACVR2B/Fc, a synthetic peptide inhibitor of ACVR2B." (PMID 33200567, 2020). "Follow‐up analysis revealed that 116 of these genes were differentially expressed in tumour hosts receiving ACVR2B/Fc compared with the untreated tumour bearers." (PMID 33200567, 2020). "ACVR2B/Fc administration to tumour hosts (A + T) was able to maintain body weight over the course of the experiment, yielding a 14% increase (P < 0.0001) in carcass weight compared with T, while not having an effect on either wet or dry food consumption." (PMID 33200567, 2020). "Treatment of the tumour group with ACVR2B/Fc significantly protected against systolic dysfunction, evidenced by EF% and FS%, along with measures of cardiac dilation and associated changes in volume." (PMID 33200567, 2020). "RNA sequencing analysis of heart muscle revealed rescue of genes related to cardiac development and contraction in tumour hosts treated with ACVR2B/Fc." (PMID 33200567, 2020). "In the present study, we did not observe any beneficial effect associated with inhibition of ACVR2B on the expression of down‐regulated mitochondrial proteins including OPA1, PGC1α, and VDAC in tumour hosts." (PMID 33200567, 2020). "Although chemotherapy is always clinically administered in the context of a tumor, our goal in this preclinical study was to specifically understand the interaction of ACVR2B/Fc with the cachexia-inducing mechanisms driven by chemotherapy." (PMID 31438622, 2019). "In a clinical setting, patients receiving chemotherapy will always have a tumor burden, but in this pre-clinical study, our focus was specifically on the metabolic interactions between ACVR2B/Fc and chemotherapy." (PMID 31438622, 2019). "Consistent with previous studies, they found that treatment of tumor-bearing mice with ACVR2B/Fc lead to a significant preservation of lean body mass, but they observed minimal metabolic alterations on top of those induced by the tumor." (PMID 31438622, 2019). "In fact, they only observed one metabolite, methyl phosphate, which was altered by the tumor and then rescued by ACVR2B/Fc treatment." (PMID 31438622, 2019). "Additionally, ACVR2A expression was similar between normal pancreas and tumor, whereas ACVR2B was downregulated in the tumors." (PMID 37083240, 2023). "Receptor ACVR2B was involved in 3 of the 15 top-scoring tumor-to-tumor interactions." (PMID 36676129, 2023). "ACVR2B represents the common receptor in 3 of the 15 top-scoring tumor-to-tumor interactions." (PMID 36676129, 2023). "Additionally, SCGB1A1, also known as uteroglobin, was reduced 70‐fold in tumour‐bearing mice and increased 44 678‐fold in tumour mice receiving ACVR2B/Fc." (PMID 33200567, 2020). "Similarly, GLP1R was reduced 51‐fold in the tumour‐bearing mice and increased 71‐fold in ACVR2B/Fc‐treated HCT116 hosts." (PMID 33200567, 2020).